PDCD1 (programmed cell death 1)
Diseases named in the same sentence as PDCD1 in open-access papers (continued):
Sharing a sentence is not in itself a finding about the gene and the disease.
metastatic melanoma (100 papers, 2015 to 2026). A melanoma that has spread from its primary site to another anatomic site. "In this study we retrospectively evaluated the association of polymorphisms in PDCD1 with responses and survival in patients with metastatic melanoma treated with anti-PD-1 monoclonal antibodies." (PMID 34177913, 2021). "Currently, the blockade of certain immune checkpoints such as the cytotoxic T-lymphocyte-associated protein 4 (CTLA-4) and programmed cell death-1 (PD-1) using checkpoint inhibitors is standard of care in patients with metastatic melanoma, especially with BRAF wild-type." (PMID 30828569, 2019). "A phase 1 clinical trial was recently performed to evaluate the feasibility and safety of FMT and reinduction of anti-PDCD1 immunotherapy in patients with anti-PDCD1 refractory metastatic melanoma." (PMID 35463305, 2022). "Therapeutic options are needed for metastatic melanoma refractory to therapies directed against programmed cell death-1." (PMID 36045435, 2022). "Immunotherapy targeting T-cell inhibitory receptors, namely programmed cell death-1 (PD-1) and/or cytotoxic T-lymphocyte associated protein-4 (CTLA-4), leads to durable responses in a proportion of patients with advanced metastatic melanoma." (PMID 33202676, 2020). "We describe a case of sequential immune-related adverse events (irAEs) in a patient with metastatic melanoma treated with single-agent anti-programmed cell death-1 (PD-1) therapy, pembrolizumab." (PMID 31511075, 2019). "We report a case of HLH in a 58-year-old metastatic melanoma patient who was undergoing immune checkpoint blockade with pembrolizumab, a programmed cell death-1 (PD-1) receptor inhibitor." (PMID 29871698, 2018). "Clinical benefit from programmed cell death 1 (PD-1) immune checkpoint blockade is limited to a subset of metastatic melanoma patients, so there is a need for predictive biomarkers." (PMID 30400835, 2018). "Antibodies blocking programmed cell death 1 (PD-1) have encouraging responses in patients with metastatic melanoma." (PMID 28137295, 2017). "So far, CTLA4 (cytotoxic T-lymphocyte protein 4; Ipilimumab) and PD-1 (programmed cell death 1; Nivolumab, Pembrolizumab) axis targeting immune checkpoint inhibitors have been approved for the treatment of metastatic melanoma." (PMID 28374234, 2017). "The other checkpoint inhibitors, pembrolizumab and nivolumab, are humanized monoclonal antibodies against programmed cell death 1 (PD-1), and are approved for use in metastatic melanoma." (PMID 26646075, 2015). "Despite the success of immune checkpoint inhibitors that target cytotoxic lymphocyte antigen-4 (CTLA-4) and programmed-cell-death-1 (PD-1) in the treatment of metastatic melanoma, there is still great need to develop robust options for patients who are refractory to first line immunotherapy." (PMID 34944961, 2021). "Immune checkpoint inhibitors that target Programmed Cell Death-1 (PD-1; pembrolizumab and nivolumab) were initially licensed for use in metastatic melanoma, and are now approved for use in renal cell carcinoma and small cell lung cancer, with further trials underway." (PMID 34584157, 2021). "Over the last decade, treatment of metastatic melanoma has profoundly improved due to the introduction of immune checkpoint inhibitors (ICI) against cytotoxic T-lymphocyte-associated protein 4 (CTLA4) and programmed cell death 1 (PD1)." (PMID 32929554, 2021). "Further studies and ongoing trials suggest that combination immunotherapy, pairing ipilimumab with the programmed cell death 1, PD-1, monoclonal antibody, nivolumab, prolongs progression-free survival in untreated metastatic melanoma patients compared to either nivolumab alone or ipilimumab alone." (PMID 29088901, 2017).
metastatic melanoma (continued). "The blockade of cytotoxic T lymphocyte antigen-4 (CTLA-4), programmed cell death-1 (PD-1), or its ligand PD-L1 with monoclonal antibodies (e.g., ipilimumab, pembrolizumab, or nivolumab) considerably prolongs the survival of patients with advanced or metastatic melanoma." (PMID 35087523, 2021). "In 2012 nivolumab-a mAb against programmed cell death 1 (PD-1)-improved progression-free survival, overall survival, demonstrated an increased response rate and could achieve an up to 35% long term survival in patients with metastatic melanoma." (PMID 28350340, 2017). "Nevertheless, immune checkpoint inhibitor therapy has revolutionized the treatment for both locally advanced and metastatic melanoma by targeting the cytotoxic T-lymphocyte antigen 4 (CTLA-4) and the programmed cell death 1 (PD1) proteins." (PMID 36142629, 2022). "Over the last decade, anti-programmed cell death 1 (PD1) antibodies (Abs) and ICIs, in combination with or without another drugs such as anti-CTLA-4 Abs, have been widely used for the treatment of advanced and metastatic melanoma." (PMID 37795022, 2023). "Although the introduction of programmed cell death 1 (PD-1) immune checkpoint inhibitors (ICIs) has significantly improved the overall survival (OS) in patients with metastatic melanoma, a substantial number of patients do not benefit from ICIs." (PMID 33803602, 2021). "Immune checkpoint inhibitors (ICIs) such as anti-PD1 (programmed cell death 1) and anti-CTLA4 (cytotoxic T lymphocyte antigen 4) antibodies have revolutionized the therapeutic landscape of metastatic melanoma and are approved as first-line therapies in the advanced as well as the adjuvant setting." (PMID 34208218, 2021).
breast cancer (98 papers, 2013 to 2026). A primary or metastatic malignant neoplasm involving the breast. "In a recent study, Zeng demonstrated that FOXO1, a gene significantly associated with PDCD1, downregulated copper homeostasis is a novel indicator of breast cancer prognosis and immune response." (PMID 37670938, 2023). "Polymorphisms of the PDCD1 have been studied also in breast cancer." (PMID 33519815, 2020). "The prognosis of breast cancer (BC) was associated with the expression of programmed cell death-1 (PD-1)." (PMID 35233733, 2022). "In previous studies, the significant associations of heterozygous genotype of PDCD1 rs2227982 and HAVCR2 rs13170556 with the risk for breast cancer and the outcomes of HCV infection were reported, respectively." (PMID 38723011, 2024). "As the positive results of multiple clinical trials were released, the Programmed cell death 1 (PD-1) and Programmed cell death ligand 1 (PD-L1) inhibitors emerge as the focus of integrative breast cancer treatment." (PMID 38577606, 2024). "PANACEA was a single-arm, phase 1b-2 study in which patients with trastuzumab-resistant advanced breast cancer were treated with the programmed cell death 1 (PD1) inhibitor pembrolizumab in combination with trastuzumab." (PMID 36010990, 2022). "Immune checkpoint inhibitors (ICI) targeting programmed cell death-1 (PD-1) or cytotoxic T lymphocyte antigen-4 (CTLA-4) pathways have made great progress in breast cancer treatment." (PMID 34631507, 2021). "In a recent phase-III randomized controlled trial (IMpassion130), patients with breast cancer were successfully treated with programmed cell death-1 (PD-1)." (PMID 34762599, 2021). "Few studies have evaluated the expression of the programmed cell death-1 and its ligand-1 (PD-L1) in breast cancer." (PMID 32216835, 2020). "Neratinib plus valproate also enhanced the efficacy of a programmed cell death-1 (PD-1) antibody in a mouse syngeneic breast cancer model." (PMID 31141894, 2019). "Some SNPs in six immunological genes, BTLA, ITGAL, CTLA4, ICOS, PDCD1, and VTCN1 were reported as breast cancer risk mutations in previous studies." (PMID 27911271, 2017). "A photodynamic immunostimulator (PCS) designed to simultaneously down-regulate and block programmed cell death 1 (PD-L1) ligand in tumor cells enables effective inhibition of breast cancer growth by photodynamic therapy (PDT) and activation of the systemic immune response." (PMID 39057071, 2024). "We found that SLAMF6 expression was highly correlated not only with the expression of T-cell markers (CD3E, CD8B, CD8A, and CD4) but also with upregulation of TCF7, PDCD1 encoding PD-1, GZMK, and effector-associated genes including IFNG and PRF1 in breast cancer." (PMID 38287061, 2024). "In recent years, incorporating immune checkpoint inhibitors (ICIs) that target programmed cell death 1 (PD-1) with its ligand PD-L1 has emerged as a promising neoadjuvant treatment strategy in early-stage solid tumors, such as breast cancer, lung cancer, and ESCC." (PMID 38566201, 2024). "In breast cancer, acetylcholine activates muscarinic receptors on tumor-infiltrating lymphocytes to reduce their expression of PD-1 (also known as PDCD1) in vivo, leading to suppressed tumor growth due to the removal of the immune checkpoint and consequent increase in the anti-tumor immune response." (PMID 36621886, 2023). "Conversely, in breast cancer, mast cells recruited and activated by tumor cells can induce transcriptional changes in genes such as SPP1, PDCD1, IL17A, TGFB1, KITLG, and IFNG, leading to anti-tumor effects." (PMID 40495762, 2025). "In inflamed cancer types including breast cancer, NcDase expression correlated strongly with the expression of the markers of immune regulation (CTLA4, LAG3, PDCD1, SIGLEC15)." (PMID 38302493, 2024). "On immune checkpoint genes in breast cancers, POGLUT2 was positively correlated with CTLA4, CD274, TIGIT, LAG3, and PDCD1." (PMID 36158688, 2022).
breast cancer (continued). "Lately, the histology-agnostic approval of ICB immunotherapy with pembrolizumab -an anti-programmed cell death-1 (PD-1) drug- for unresectable or metastatic dMMR or MSI-H solid tumors, increased the importance of assessing MMR status in breast cancer." (PMID 34001143, 2021). "Other studies have explored the expression of the Programmed Cell Death 1 (PD1)/Programmed Cell Death Ligand 1 (PD-L1) immune checkpoint pathway in TNBC and other breast cancer subtypes." (PMID 32210163, 2020). "Moreover, we found six sex-biased genes (EGFR, CDK6, PRKCB, PDCD1, KCNH2, FCGR3B, and TOP2A) in BRCA were the therapeutic targets of breast cancer." (PMID 39175079, 2024). "In recent years, there has been a growing body of research on the efficacy of checkpoint inhibitors with breast cancers, specifically antibodies against cytotoxic T-lymphocyte antigen-4 (CTLA-4), programmed cell death-1 protein (PD-1) and programmed cell death ligand-1 (PD-L1)." (PMID 37860001, 2023). "The triple-negative mouse breast cancer cell line 4T1 is resistant to programmed cell death-1/ligand 1 antibody therapy." (PMID 37011280, 2023). "Additionally, we found that FOXP3 had a significant positive correlation with PDCD1, CD274, CTLA4 and TMB in breast cancer." (PMID 35614183, 2022). "Additionally, FOXP3 has a significant positive correlation with PDCD1, CD274, CTLA4 and TMB in breast cancer, and FOXP3 expression showed a statistically significant correlation with infiltration of immune cells." (PMID 35614183, 2022). "Triple-negative breast cancer (TNBC) is a particularly aggressive subtype of breast cancer, which is relatively resistant to anti-programmed cell death-1 (α-PD1) therapy, characterized as non-immunogenic, dense stroma and accumulation of M2 tumor-associated macrophages (TAMs)." (PMID 35812418, 2022). "Indeed, the overall response rate of ER+, HER2 negative breast cancer to pembrolizumab, an antibody targeting programmed cell death-1/programmed death ligand-1, is only about 12%." (PMID 35263321, 2022). "In the present study, MYL5 expression negatively correlated with the markers of T cells exhaustion, such as PDCD1 (PD-1), CD274 (PD-L1), and CTLA4 (cytotoxic T-lymphocyte antigen 4), which indicated that MYL5 could play a positive role in prolonging survival prognosis for breast cancer patients." (PMID 36846347, 2023). "The results showed that in breast cancer, GPS1 expression was positively correlated with LAG3, PVRL2, and LGALS9, and negatively correlated with CD274 and HAVCR2, but not with CTLA4 and PDCD1." (PMID 38289496, 2024). "By mass spectrometry analysis performed in a breast cancer stem cell model (human mammary epithelial HMLER CD24low/CD44high), salinomycin, a ferroptosis inducer, was capable of inducing protein upregulation of CD274 and TNFAIP3 without any modulation of PDCD1." (PMID 38201582, 2023).
hepatocellular carcinoma (97 papers, 2015 to 2026). A malignant tumor that arises from hepatocytes. "Expression levels of PDCD1 mRNA encoded by haplotypes were investigated by quantitative PCR in hepatocellular carcinoma (HCC) tissue and peripheral blood mononuclear cells." (PMID 32937024, 2021). "The liver function reserve has a significant impact on the therapeutic effects of anti-programmed cell death-1 (PD-1) for hepatocellular carcinoma (HCC)." (PMID 38834790, 2024). "Our current findings suggest that PDCD1 is upregulated in hepatocellular carcinoma and shows an inverse correlation with PDE7B expression." (PMID 39640266, 2024). "Through transcriptome sequencing analysis, we identified PDCD1 as a potential target of PDE7B in hepatocellular carcinoma." (PMID 39640266, 2024). "Clinical characteristics of 56 patients with unresectable hepatocellular carcinoma receiving tyrosine kinase inhibitors combined with programmed cell death-1 inhibitors therapy." (PMID 38464731, 2024). "Pembrolizumab (Keytruda) is marketed for the treatment of hepatocellular carcinoma in USA and Europe and is an antineoplastic immunomodulating molecule that antagonist mechanism on Programmed Cell Death Protein 1 (PD1 or CD279 or PDCD1)." (PMID 39273237, 2024). "Despite remarkable advancements in cancer immunotherapy, the overall response rate to anti-programmed cell death-1 (anti-PD-1) therapy in hepatocellular carcinoma (HCC) patients remains low." (PMID 37968706, 2023). "The most significant immune biomarkers for hepatocellular carcinoma were employed in immunotherapy, according to earlier research: PDCD1, CTLA4, HAVCR2/TIM3, and LAG3." (PMID 38248311, 2023). "Immune evasion through up-regulation of programmed cell death-1 (PD-1) pathway is a pivotal mechanism in the progression of hepatocellular carcinoma (HCC), a disease characterised by dismal prognosis and limited treatment options." (PMID 31061454, 2019). "Programmed cell death-1/programmed cell death-ligand 1 (PD-[L]1) inhibitors plus bevacizumab (or biosimilars) or tyrosine kinase inhibitors (TKIs) have been widely used for the first-line treatment of patients with unresectable hepatocellular carcinoma (uHCC)." (PMID 40625746, 2025). "This study evaluated the effects of PDCD-1 (rs10204525 and rs36084323), and LAG3 (rs870849 and rs1882545) gene polymorphisms on hepatocellular carcinoma (HCC) risk." (PMID 37131179, 2023). "We evaluated the effect of PDCD-1 and LAG3 gene polymorphisms on the risk of hepatocellular carcinoma (HCC) in this study." (PMID 37131179, 2023). "Nivolumab and pembrolizumab disrupt the programmed cell death-1 immune checkpoint and display promising efficacy and safety results in advanced hepatocellular carcinoma (HCC)." (PMID 34868952, 2021). "Programmed cell death-1 (PD-1) is involved in hepatitis B virus (HBV) infection, the leading cause of hepatocellular carcinoma (HCC) worldwide." (PMID 25895129, 2015). "Immune checkpoint inhibitors (ICIs) targeting the programmed cell death-1 (PD1)/programmed cell death ligand-1 (PDL1) pathway constituted the backbone of systemic therapy for patients with un-resectable hepatocellular carcinoma (HCC)." (PMID 37858184, 2023). "Three maker genes were found in liver carcinoma of HPA database (TREM2 and GPR34 from macrophage, PDCD1 from Treg cell), which indicated that macrophages and Treg cells existed in liver carcinoma." (PMID 36221095, 2022). "In a recent report where immunotherapy was used for patients with advanced hepatocellular carcinoma (HCC), PARG inhibition was shown to have a synergistic effect with anti-programmed cell death 1 (PD1) therapy." (PMID 37858678, 2023). "In recent years, immunotherapy, including anti-programmed cell death 1/programmed cell death 1 ligand 1 treatment, has emerged as a potential approach to reach satisfactory modulation for the progression of NAFLD and treatment of NAFLD-related hepatocellular carcinoma." (PMID 37020584, 2023).
hepatocellular carcinoma (continued). "In addition, the combination of Galunisertib and Nivolmab, a new inhibitor of programmed cell death-1 (PD-1) from Merck Sharp and Dohme (MSD), for the treatment of bone marrow hyperplasia and hepatocellular carcinoma, has entered a phase III multicenter clinical trial." (PMID 31438649, 2019).